SNORD115-25 (small nucleolar RNA, C/D box 115-25)
Synonyms: HBII-52-25
Gene: Small nucleolar RNA gene on chromosome 15 (25,215,541 to 25,215,622, forward strand). Ensembl gene ENSG00000199489.
Gene Ontology:
Biological process: RNA processing
Cellular component: nucleolus
Homologues: Orthologues: macaque SNORD115 (94% identical). Paralogues in human: SNORD115-12 (96% identical), SNORD115-9 (96% identical), SNORD115-10 (95% identical), SNORD115-11 (95% identical), SNORD115-13 (95% identical), SNORD115-20 (95% identical), SNORD115-29 (95% identical), SNORD115-36 (95% identical), SNORD115-40 (95% identical), SNORD115-42 (95% identical), SNORD115-43 (95% identical), SNORD115-5 (95% identical), and 37 more.